SOCS1 (suppressor of cytokine signaling 1)
Diseases named in the same sentence as SOCS1 in open-access papers (continued):
Sharing a sentence is not in itself a finding about the gene and the disease.
type 2 diabetes (9 papers, 2015 to 2026). "The involvement and change of gene expression of CACNA1G, IGF2, MLH1, and SOCS1, in addition to causing CRC, can cause diseases such as type 2 diabetes, Fanconi’s anemia, and toxoplasmosis." (PMID 38874740, 2024). "Increased IRS1 ubiquitination and its subsequent degradation have been reported in a mouse model of type 2 diabetes (TALLYHO/Jng mice) and were associated with an increase in SOCS1 levels." (PMID 26965244, 2016). "It has been suggested that S. aureus superantigen SEA might induce Type II diabetes by increasing the expression level of SOCS1." (PMID 34564613, 2021). "in 2018 investigated potential binders of SOCS1 through the lens of therapeutics for type 2 diabetes mellitus (T2DM)." (PMID 39676878, 2024). "For instance, SOCS1 degrades IRS1 and IRS2, required for insulin signaling, via the SOCS Box domain, thus, limiting its potential in type-2 diabetes." (PMID 31105556, 2019). "In addition, the KEGG analysis indicated that SOCS1 played a vital role in the JAK-STAT signaling pathway and in type II diabetes mellitus." (PMID 35096054, 2022).
ZIKV infection (9 papers, 2019 to 2023). "Representative Western blot analysis and quantification data confirmed the higher ZIKVPE243-mediated SOCS1 protein expression at the early phase of ZIKV infection (12 and 24 hpi)." (PMID 37376550, 2023). "The antiviral profile suggests that the PC3 cells modulate the antiviral response through the suppressor molecule expression, SOCS-1, during a ZIKV infection." (PMID 36557673, 2022). "Following ZIKV infection of NPCs, there is increased expression of SOCS1 and 3 and a reduction of type I and III IFN responses." (PMID 35215978, 2022). "The inhibition of AXL during a ZIKV infection in Sertoli cells causes: (i) the inactivation of STAT1, (ii) the reduction of SOCS-1, and (iii) an interferon-induced antiviral gene (ISG) expression that decreases the viral replication." (PMID 36557673, 2022). "Upon ZIKV infection, the expression levels of SOCS1 and SOCS3 were upregulated in a manner dependent on post-infection timepoints." (PMID 32120897, 2020). "SOCS1 transcript levels were significantly elevated upon ZIKV infection at 48 hpi, and decreased thereafter." (PMID 32120897, 2020). "Increased expression of the IFNλ heterodimeric receptor complex and negative regulators SOCS1/3 were also observed during ZIKV infection." (PMID 31289325, 2019). "Provided that the recently developed SOCS1/3 antagonist has a potent antiviral function against a broad group of viruses, such as herpes simplex virus-1, vaccinia virus, and influenza virus, it will be interesting to evaluate the effect of these antagonists against ZIKV infection." (PMID 32120897, 2020). "In the current study, both SOCS1 and SOCS3 transcript levels were significantly elevated upon ZIKV infection, and the induction levels were similar for the African and Asian lineages." (PMID 32120897, 2020). "Our result suggests that ZY13 administration downregulates the expression of Axl, SOCS1 and SOCS3 at early stage post ZIKV infection." (PMID 32849457, 2020). "ZIKV infection also increased expression of mRNAs for both IFNLR1 and IL10RB components of the IFNλ heterodimeric receptor complex and the SOCS1 and SOCS3 negative regulators of IFN signaling." (PMID 31289325, 2019). "As ZIKV infection resulted in the upregulation of both SOCS1 and SOCS3 expression, SOCS1 or SOCS3 was overexpressed in A549 cells in order to further evaluate the functional roles of SOCS1 and SOCS3 in viral replication." (PMID 32120897, 2020). "In addition, western blot results confirmed the upregulation of SOCS1 and SOCS3 protein levels triggered during the early phases of ZIKV infection." (PMID 32120897, 2020). "SOCS1 and SOCS3 expression increased at 4 hpi and continued to increase at later timepoints; a finding which indicates the early induction of SOCS expression subsequent to ZIKV infection." (PMID 32120897, 2020). "During a ZIKV infection in Sertoli cells, the transcription factor STAT1, an important molecule in the AXL-IFNAR signaling pathway, is activated; promoting the expression of suppressor of cytokine signaling 1 (SOCS1) and the restriction of the interferon response." (PMID 36557673, 2022). "Therefore, to investigate whether Axl kinase augments ZIKV infection of human SC by negatively regulating antiviral response, we first evaluated the effect of R428 treatment on protein levels of STAT1/p-STAT1 (phosphorylated STAT1), SOCS1, and SOCS3." (PMID 31311882, 2019).
dengue (8 papers, 2017 to 2023). "Additionally, a close association between cytokine imbalance and SOCS1/3 observed in patients with a severe dengue infection suggested that the combined analysis of SOCS1/3, IL-10, and IL-6 expression levels could identify at-risk patients for severe dengue." (PMID 32120897, 2020). "Furthermore, an imbalance of IL-10 and IL-6, and SOCS1/3 has been observed in patients with severe dengue virus infection." (PMID 37376550, 2023). "The reports suggest that SOCS-1 protein is dysregulated in dengue patients and might be one of the contributing factors toward cytokine storm during dengue pathogenesis." (PMID 33330133, 2020). "Indeed, it is recognised that miR-150 is able to negatively regulate SOCS1, a suppressor of cytokine signalling whose aberrant expression could lead to cytokine dysregulation, as reported in dengue patients." (PMID 34359957, 2021). "In light of the demonstrated association between SOCS1 and miR-150, it is tempting to speculate that by controlling the overexpression of miR-150 in dengue patients, the expression of SOCS1 could be restored and the dysregulation in cytokine expression was rescued." (PMID 31898495, 2020). "Interestingly, they showed a reciprocal correlation between SOCS1 expression and dengue severity." (PMID 31898495, 2020). "Quantitative PCR was used to measure SOCS1 mRNA and its regulatory influence on miRNA levels in PBMCs obtained from the blood of patients with non-hemorrhagic dengue fever (DF) vs DHF." (PMID 31214179, 2019).
lung adenocarcinoma (8 papers, 2020 to 2026). A carcinoma that arises from the lung and is characterized by the presence of malignant glandular epithelial cells. "Analysis of The Cancer Genome Atlas Program (TCGA) dataset revealed that patients with stage IV lung adenocarcinoma had lower SOCS1 expression than those with stage I." (PMID 38521953, 2024). "In this study, we found that 3B1A and NCI-H1573 cell lines, representative of advanced stages of lung adenocarcinoma, constitutively express SOCS1." (PMID 39596207, 2024). "PRDM5 repression in lung adenocarcinoma cell lines suppressed the expression of SOCS1, thereby regulating downstream signaling pathways or target proteins." (PMID 36127737, 2023). "Our study suggests that the low expression of PRDM5 promotes the proliferation of lung adenocarcinoma cells by downregulating SOCS1 and then upregulating the JAK2/STAT3 signaling pathway." (PMID 36127737, 2023). "Our study suggests that deregulation of PRDM5 promotes the proliferation of lung adenocarcinoma cells by downregulating SOCS1 and then upregulating the JAK2/STAT3 signaling pathway." (PMID 36127737, 2023). "These suggest ubenimex as a promising treatment for lung adenocarcinoma and SOCS1 as a new molecular target for diagnosing and treating lung adenocarcinoma." (PMID 35789603, 2022). "IL-6 and SOCS1 are critical regulators of CD155 expression in lung adenocarcinoma." (PMID 39596207, 2024). "Our results suggest that SOCS1 could be of particular relevance as a prognostic biomarker for the success of immunotherapies because it regulates the overexpression of CD155 in lung adenocarcinoma." (PMID 39596207, 2024). "Importantly, the expression level of SOCS1 was different between CDDP-susceptible and CDDP-resistant lung adenocarcinoma cell lines." (PMID 37916165, 2023). "The results above indicated that inhibition of the JAK2/STAT3 pathway triggered by SOCS1 might be mediated by PRDM5 in lung adenocarcinoma cells." (PMID 36127737, 2023). "This study showed that treatment with ubenimex alone or combined with pemetrexed could considerably increase the expression level of SOCS1 in patients' serum, lung adenocarcinoma cells, and mouse tumor tissues and inhibit the JAK2/STAT3 signaling pathway." (PMID 35789603, 2022). "Overall, combination therapy with UBE and PEM could inhibit the JAK2-STAT3 signaling pathway by upregulating SOCS1 expression to hinder the progression of lung adenocarcinoma cells." (PMID 35789603, 2022). "Thus, we evaluated SOCS1 expression in lung adenocarcinoma cell lines." (PMID 39596207, 2024). "These suggest that ubenimex combined with pemetrexed in lung adenocarcinoma treatment could be therefore achieved by upregulating SOCS1 expression and then inhibiting the JAK2-STAT3 signaling pathway, further confirming the negative regulatory effect of SOS1 on the JAK2/STAT3 signaling pathway." (PMID 35789603, 2022). "Our findings suggest that ubenimex alone or in combination with pemetrexed could inhibit the occurrence and development of malignant biological behavior of lung adenocarcinoma cells by upregulating SOCS1 expression and then inhibiting the JAK2-STAT3 signaling pathway." (PMID 35789603, 2022). "According to our results, overexpressed PRDM5 is likely to upregulate the promoter activity of SOCS1 and further suppress the JAK2/STAT3 pathway by inhibiting the phosphorylation of JAK2 and STAT3, thus repressing cell proliferation in lung adenocarcinoma." (PMID 36127737, 2023). "Furthermore, we found that this inverse relationship between SOCS1 and CD155 was maintained in the TCGA lung adenocarcinoma cohort." (PMID 39596207, 2024). "However, further basic and clinical studies are needed to examine SOCS1 alterations and to precisely identify its molecular mechanism after CDDP exposure in lung adenocarcinoma and its relationship with treatment efficacy." (PMID 37916165, 2023).
lung adenocarcinoma (continued). "Data from the lung adenocarcinoma cohort from TCGA showed that patients with high SOCS1 expression showed low CD155 expression, and patients with low SOCS1 expression displayed high CD155 expression, suggesting that SOCS1 may negatively regulate CD155 expression." (PMID 39596207, 2024). "Interestingly, the lung adenocarcinoma cell lines that displayed low expression of the negative regulator Suppressor of Cytokine Signaling 1 (SOCS1) showed increased CD155 expression after IL-6 stimulation, in contrast to those that showed high SOCS1 expression." (PMID 39596207, 2024).
Hepatitis (7 papers, 2010 to 2025). Inflammation of the liver. "Selective hepatocyte depletion of SOCS1 in liver-specific SOCS1 knockout mice resulted in enhanced concanavalin A-induced hepatitis associated with pro-apoptotic signals (including STAT1 and JNK)." (PMID 26891124, 2016). "It was also shown that endogenous SOCS1 participate in the prevention of liver diseases such as hepatitis, fibrosis, and cancers." (PMID 29018442, 2017). "Collectively, SOCS1 expression in the liver prevents fatal hepatitis via the suppression of exacerbated liver inflammation." (PMID 20862390, 2010). "Compared to wild type mice, mice with specific deletion of SOCS1 in hepatocytes (hepatocyte-specific SOCS1 conditional KO mice) exhibit severe ConA-induced hepatitis with increased mortality." (PMID 20862390, 2010). "SOCS1 expression is also important for suppression of hepatitis in adult mice." (PMID 20862390, 2010). "In accordance with this, mice lacking SOCS1 are sensitive to a variety of liver diseases including hepatitis, liver cirrhosis, and HCC." (PMID 20862390, 2010).
lung fibrosis (7 papers, 2014 to 2024). "Another study in rats suggested that STAT1 inhibits bleomycin-induced lung fibrosis, while reduced SOCS1 expression has been linked to pulmonary fibrosis in patients and in animal models." (PMID 27834824, 2016). "It was reported that lower levels of SOCS1 mRNA and higher amounts of type I collagen were produced by fibroblasts from lungs of patients with pulmonary fibrosis as compared with those from healthy lungs." (PMID 29085365, 2017). "A role of SOCS1 in lung fibrosis was supported by another study using SOCS1-haplodeficient (+/-) mice in a bleomycin induced model of lung fibrosis." (PMID 24478703, 2014). "In this study, bleomycin challenged SOCS1-haplodeficient mice developed significantly increased pulmonary fibrosis as compared to wild type mice further supporting that altered gp130 signaling can exacerbate a fibrotic response." (PMID 24478703, 2014). "Therefore, SOCS1 might suppress pulmonary fibrosis by inhibiting profibrotic cytokines and collagen synthesis of lung fibroblasts." (PMID 29085365, 2017). "In liver cirrhosis and idiopathic pulmonary fibrosis, miR-142-5p prolongs STAT6 phosphorylation by inhibiting suppressor of cytokine signaling 1 (SOCS1) protein, leading to increased IgE, eosinophil infiltration, fibroblast proliferation and collagen synthesis, and aggravates tissue fibrosis." (PMID 35634335, 2022).
nasopharyngeal carcinoma (7 papers, 2019 to 2025). A carcinoma arising from the nasopharyngeal epithelium. "In a nasopharyngeal carcinoma (NPC) model, STING increased SOCS1 expression in tumor cells and MDSCs, inhibiting NPC-derived MDSC induction." (PMID 40297580, 2025). "In nasopharyngeal carcinoma, LINC00669 protects SOCS1 from ubiquitinating STAT1, which promotes cancer cell proliferation and invasion." (PMID 34527677, 2021). "Of note, the dysregulation of lncRNAs was associated with the tumor formation and progression in many human malignancies including NPC, such as linc00669 promotes nasopharyngeal carcinoma cell proliferation and invasion via competitively combining to the suppressor of cytokine signaling (SOCS1)." (PMID 35378932, 2022).
osteoarthritis (7 papers, 2011 to 2022). A noninflammatory degenerative joint disease occurring chiefly in older persons, characterized by degeneration of the articular cartilage, hypertrophy of bone at the margins and changes in the synovial membrane. "Few studies have shown that IL-4 is associated with the pathological process of osteoarthritis; accordingly, we mainly explored the expression of IL-4 and the relationship between IL-4 and SOCS1 in IL-1β-stimulated human osteoarthritic chondrocytes." (PMID 28373981, 2017). "Recently, Suppressor of Cytokine Signaling 1 (SOCS1) was identified as a potential therapeutic target for osteoarthritis (OA) treatment." (PMID 28373981, 2017). "For example, SOCS1 was up-regulated in the synovial membranes from patients with RA when compared with osteoarthritis." (PMID 26310571, 2015). "SOCS1 was also showed to be upregulated in the synovial membranes of patients with RA compared to patients with osteoarthritis." (PMID 21510883, 2011). "It stabilizes SOCS1, an important negative regulator of cytokine signaling, and JOSD1 mRNA is upregulated in high-grade osteoarthritis cartilage, suggesting a protective role for JOSD1 in osteoarthritis." (PMID 33473114, 2021).
type 1 diabetes (7 papers, 2016 to 2025). "Both type I IFNs and IL-21 regulate SOCS1 expression in T cells and both regulate the development of type 1 diabetes in NOD mice." (PMID 31653894, 2019). "For this we employed an experimental model for CVB-induced type 1 diabetes, the SOCS-1-tg mouse." (PMID 40760251, 2025). "Interestingly, expression of SOCS-1, -2, and -3 proteins is upregulated in islet cells from human type 1 diabetes (T1D) patients compared to healthy controls." (PMID 27242781, 2016). "In animal models of type 1 diabetes, SOCS1 has been suggested to be involved in the regulation of inflammatory cytokines such as IFN-γ and tumor necrosis factor alpha, which are responsible for the destruction of pancreatic β cells, and SOCS1 may protect β cells from cytokine-mediated destruction." (PMID 37110462, 2023).
allergic disease (6 papers, 2011 to 2025). An immune response that occurs following re-exposure to an innocuous antigen, and that requires the presence of existing antibodies against that antigen. "The mechanism may also be modulated by disease phenotype, as the presence of type 2 cytokines in allergic disease inhibit IFN production [potentially via increased suppressor of cytokine signaling-1 (SOCS1) expression]." (PMID 32499788, 2020). "SOCS1 is commonly silenced in inflammatory diseases, and over-expression of SOCS3 correlates with allergies." (PMID 26090929, 2015).
B-cell lymphoma (6 papers, 2016 to 2024). "SOCS1 represents a key inhibitor of JAK-STAT signaling and inactivating SOCS1 mutations have been reported in subsets of B-cell lymphomas including EBV-associated DLBCLs in HIV-infected individuals." (PMID 36604606, 2023). "On the other hand, deleterious SOCS1 mutations have been detected in both primary mediastinal B-cell lymphoma and classical Hodgkin lymphoma." (PMID 30453988, 2018).
Crohn disease (6 papers, 2007 to 2024). A gastrointestinal disorder characterized by chronic inflammation involving all layers of the intestinal wall, noncaseating granulomas affecting the intestinal wall and regional lymph nodes, and transmural fibrosis. "Two emerge with highly significant GRAIL scores: rs8178556 on chromosome 21 (IFNAR1, ptext = 1.7×10−4) and rs12928822 on chromosome 16 (SOCS1, ptext = 8.2×10−4) suggesting these independent regions may lead to novel associated SNPs for Crohn's disease." (PMID 19557189, 2009). "Patient 2 initially presented with gastrointestinal symptoms, without histological resembling of Crohn's disease, which has been observed in SOCS1 deficiency." (PMID 39840313, 2024). "The present observations of Crohn’s disease-like ileo-colic chronic inflammation in P1 and CIPO caused by lymphocytic leiomyositis in P2 expands the phenotypic spectrum of SOCS1 HI and further stress the importance to strictly control the JAK-STAT pathway to preserve intestinal homeostasis." (PMID 37156989, 2023).
Hyperglycemia (6 papers, 2018 to 2023). An increased concentration of glucose in the blood. "Importantly, we linked increased SOCS-1 expression to impaired host defense in a model of hyperglycemia." (PMID 33690673, 2021). "A recent study described that miRNA-155 deficiency promotes nephrin acetylation and decreases renal damage in hyperglycemia induced nephropathy, effects that were associated with inhibited IL-17A production through enhancement of suppressor of cytokine signaling 1 (SOCS1) expression." (PMID 31963845, 2020). "Experimental studies have shown that suppressing miR-155 expression in DKD mice protects against kidney damage, attenuates hyperglycaemia-induced kidney damage and downregulates IL-17 expression by enhancing the suppression of cytokine signalling 1 (SOCS1)." (PMID 36675311, 2023). "Notably, we unveiled that hyperglycemia triggers aberrant SOCS-1 expression that correlates with decreased overall IFN signatures in the infected skin." (PMID 33690673, 2021). "Together these data suggest that enhanced Socs1 expression during hyperglycemia is detrimental to skin host defense and that iKIR treatment could represent host-directed immunotherapy to treat these antibiotic-resistant pathogens in the skin." (PMID 33690673, 2021). "Therefore, we hypothesized that hyperglycemia enhances SOCS-1 expression and that blocking SOCS-1 actions might be a potential therapeutic approach to treat skin infections under hyperglycemic conditions." (PMID 33690673, 2021).